MIR432 (microRNA 432)
Synonyms: hsa-mir-432; MIRN432; mir-432
Gene: MicroRNA gene on chromosome 14 (100,884,483 to 100,884,576, forward strand). Ensembl gene ENSG00000272458.
Gene Ontology:
Biological process: miRNA-mediated post-transcriptional gene silencing
Homologues: Orthologues: chimpanzee ptr-mir-432 (100% identical), macaque mml-mir-432 (98% identical), dog MIR432 (87% identical), pig ssc-mir-432 (81% identical), rabbit MIR432 (72% identical), guinea pig MIR432 (66% identical).
Diseases named in the same sentence as MIR432 in open-access papers:
MIR432 is named in the same sentence as 1 disease in open-access papers, as found by Europe PMC text mining. Sharing a sentence is not in itself a finding about the gene and the disease.
MIR432 shares sentences with these, for which no sentence is quoted: neuroblastoma (1 paper).